RRM2 (ribonucleotide reductase regulatory subunit M2)
Diseases named in the same sentence as RRM2 in open-access papers (continued):
Sharing a sentence is not in itself a finding about the gene and the disease.
tumor (continued). "Unlike other tumor viruses that increase dNTP biosynthesis by inducing cell proliferation, HBV acquires dNTPs by activating the expression of cellular RRM2, a cell cycle gene that is rate-limiting for dNTP production, without inducing the cell cycle." (PMID 39339888, 2024). "Therefore, simultaneous inhibition of RRM2 by CHKi in the absence of the external electron donor Trx1 renders RNR inactive to a greater extent than CHK1i treatment alone, leading to a drastic loss of the dNTP pool that further sensitizes the anti-tumor effects of the drug." (PMID 38821952, 2024). "We also found that while RRM2 and SH3GL2 were differentially expressed in GBM, their expression had no prognostic value for GBM, suggesting that they are tumor-specific, but not GBM specific." (PMID 27655637, 2016). "Furthermore, the membrane RRM2-positive iCCA cells were sorted and they possessed CSC malignant features compared to the corresponding negative cells, revealing the tumor heterogeneity of iCCA from a new perspective." (PMID 39243109, 2024). "Interestingly, we found that RRM2 expression was positively correlated with non-structural maintenance of chromosomes condensin I complex subunit G (NCAPG), which promotes tumor development (P <0.001)." (PMID 37056349, 2023). "For further research, it is worth co-culturing tumor cells with either autologous or non-autologous immune cells, with LDH release, flow cytometry, real-time imaging or cytokine release assays using the interference of RRM2." (PMID 35740608, 2022). "Furthermore, PEG-ADI did not have any significant effect on RRM2 levels in vitro, though increased expression of one subunit in vivo; this mechanism may involve regulation of other transcriptional mediators of RRM2 that are triggered by the local tumor environment that is not recapitulated in vitro." (PMID 25499121, 2014). "Therefore, patient #8 who showed a low expression level of RRM2 did not respond to HDS may be due to a lack of binding target, further suggesting that HDS played an anti-tumor effect mainly through targeting RRM2." (PMID 35546402, 2022).
cancer (279 papers, 2008 to 2026). A tumor composed of atypical neoplastic, often pleomorphic cells that invade other tissues. "Elevated RRM2 levels have been consistently associated with poor prognosis and increased resistance to chemotherapy in diverse cancer types." (PMID 41392282, 2025). "Pan-cancer dysregulated genes and proteins were identified to develop diagnostic, pathologic, and prognostic models, with RRM2 and ADH1B emerging as robust diagnostic biomarkers." (PMID 39884577, 2025). "Ribonucleotide reductase subunit M2 (RRM2) has been implicated in the progression of various cancers, but its role in LUAD remains underexplored." (PMID 41357570, 2025). "The prognostic signature we have constructed includes TREX1, NOX4, and RRM2, with the latter two also being closely associated with cancer progression." (PMID 41346575, 2025). "First, we explored the association between RRM2 expression and the infiltration level of immune cells in TCGA cancers using the TIMER, CIBERSORT, CIBERSORT-ABS, QUANTISEQ, XCELL, MCPCOUNTER, and EPIC algorithms." (PMID 38635758, 2024). "The dysregulation of RRM1 and RRM2 has been implicated in cancer development, progression, and resistance to chemotherapy." (PMID 39682247, 2024). "Although there is evidence that ribonucleotide reductase subunit M2 (RRM2) is associated with numerous cancers, pan-cancer analysis has seldom been conducted." (PMID 38635758, 2024). "RRM2 overexpression was strongly linked with advanced patient cancer stages, with the highest RRM2 expression observed in stage 3, which corresponds to the degree of vascular invasion." (PMID 39256879, 2024). "For DFI, high RRM2 expression was linked to poor prognosis for cancers of KIRP (P = 0.007), LIHC (P = 0.038), LUAD (P = 0.005), PAAD (P = 0.022), SARC (P<0.001), TGCT (P = 0.043) and THCA (P = 0.001)." (PMID 38635758, 2024). "The splicing factorHNRNPA1, which contains two RNA recognition motifs (RRM1 and RRM2), has been linked to cancer progression by facilitating alternative splicing of PKM precursor mRNA exons." (PMID 37897508, 2024). "Numerous studies suggest that RRM2 expression was dramatically increased in various cancer tissues, causing unfavorable prognosis to these patients." (PMID 38356717, 2024). "Because of this fundamental function, alterations in RRM2 expression have been linked to several human diseases, including DNA replication-enhanced diseases such as cancers." (PMID 36768940, 2023). "Human RRM2 is known to be implicated in cancer and has functions that range from the regulation of BRCA1 to protection against ferroptosis." (PMID 37239369, 2023). "The upregulation of RRM2 has been implicated in various cancer types and is associated with poor prognosis and resistance to chemotherapy." (PMID 37968699, 2023). "The dysregulation of RRM2 has been firmly associated with diverse cancer types, rendering it an appealing candidate for cancer therapeutic interventions." (PMID 37968699, 2023). "RRM2, a stress response factor, has been associated with the initiation and advancement of various cancers." (PMID 37608887, 2023). "Overexpression of ncRNAs and RNA modification-mediated RRM2 has been associated with poor survival of malignant tumors." (PMID 36202136, 2022). "The most downregulated of these genes was RRM2, which is associated with a poor prognosis in pancreatic and lung cancers." (PMID 36359879, 2022). "The higher expression of RRM2 has also been associated with poor survival outcomes in cancer patients." (PMID 36202136, 2022). "The association of RRM2 expression with immune-related genes in cancers showed that RRM2 had a positive correlation with most chemokines, chemokine receptors, MHC genes, and immunostimulatory genes across TCGA cancer types." (PMID 35740608, 2022). "As the catalytic subunit of RR, RRM2 is the rate-limiting enzyme for DNA synthesis and repair, and its expression level is associated with the sensitivity of cancer cells to chemotherapy drugs and endocrine therapy drugs." (PMID 34895038, 2021).
cancer (continued). "The EGFR inhibitor AST1306 reversed the RRM2-induced effects on cancer cells, indicating that the function of RRM2 is associated with EGFR/AKT signaling pathway." (PMID 31696057, 2019). "By contrast, RRM2 expression was significantly associated with cell cycle-progression, consistent with its role as a RR subunit to promote cancer cell proliferation." (PMID 31637211, 2019). "Upregulation of RRM2 has been associated with cancer cell proliferation, invasion and metastasis in multiple types of cancers." (PMID 31637211, 2019). "RRM2 was identified as a diagnostic marker of several cancers, suggesting that RRM2 is a potential therapeutic target." (PMID 31673243, 2019). "show that WEE1 inhibition selectively kills H3K36me3-deficient cancer cells through dNTP starvation resulting from RRM2 depletion." (PMID 26602815, 2015). "Second, analysis of a ChIP-seq database (ENCODE) from multiple cancer cell lines showed enrichment for H3K36me3 at the RRM2 promoter." (PMID 26602815, 2015). "Consistent with what we expected, the increased vascularization caused by overexpression of RRM2 did confer a growth advantage to RRM2-overexpressing cancer cells." (PMID 19250552, 2009). "The Rrm2 gene plays a critical role in DNA synthesis and cell proliferation, with its abnormal expression closely linked to the occurrence, invasion, and drug resistance of various malignant tumors." (PMID 40863131, 2025). "Additionally, more than 20 immune checkpoint genes were associated with RRM2 expression in 10 cancer types." (PMID 38635758, 2024). "The rationale behind this strategy also exploits the intrinsic upregulation of genes involved in dNTP biosynthesis, such as those encoding TK1, RRM2 and TS, among others, which several studies have found to be among the top metabolic enzymes frequently overexpressed in several cancer types." (PMID 39206868, 2024). "For DFI, the data indicated that the high RRM2 expression was associated with the poor prognosis for cancers that included BRCA (P = 0.036), KIRP (P<0.001), LIHC (P = 0.021), LUAD (P<0.001), PAAD (P = 0.012), PRAD (P = 0.020), SARC (P = 0.002), and THCA (P<0.001)." (PMID 38635758, 2024). "Besides, contributions in the cancer field show that upregulation of RRM2 leads to higher mutation rates and promotes replication stress and tumorigenesis." (PMID 39206868, 2024). "RRM2 has been reported in many types of cancer and is associated with the development of tumors." (PMID 37056387, 2023). "RRM2 high expression was linked to a dismal OS in several cancers from GEO, including BRCA (HR = 2.41, p < 0.001), GBM (HR = 1.94, p < 0.001), LUAD (HR = 1.97, p < 0.001), LUSC (HR = 1.54, p = 0.047), PRAD (HR = 1.34, p < 0.001) and SKCM (HR = 3.46, p = 0.002)." (PMID 35740608, 2022). "We discovered that mutation and amplification were the most prevalent RRM2 alterations in pan-cancer, which may trigger the onset and development of cancer." (PMID 36518297, 2022). "Also, we confirmed that miR-197-3p/RRM2 axis was associated with OMT-induced cancer inhibition of CC cells." (PMID 35609310, 2022). "A significant association between RRM2 and most immune cells was observed across TCGA cancers." (PMID 35740608, 2022). "On the other hand, RRM2 overexpression could significantly enhance the activation potential of multiple oncogenes and increase the risk of malignant tumors." (PMID 35204799, 2022). "We analyzed the expression profiles of RRM2 and its association with prognosis in various cancers." (PMID 36518297, 2022). "Previous studies demonstrated a strong association between RRM2 expression level and cancer risk." (PMID 36518297, 2022). "Remarkably, enriched nucleosides or enhanced RRM2 expression promote tumorigenesis by suppressing oncogene-induced stable associated cell growth arrest, and dNTP repression with RRM2 knockdown could inhibit the growth of cancer cells." (PMID 34858835, 2021).
cancer (continued). "Though some regulatory factors have been introduced to regulate the expression of RRM2, the underlying mechanisms for controlling the crucial enzyme remain unclear in different cancer types." (PMID 27801665, 2016). "Therefore, the results demonstrated that RRM2 expression was notably associated with cancer immunity, though the regulation of RRM2 could vary depending on the cancer type." (PMID 36202136, 2022). "High expression of RRM2 was significantly associated with clinical stage (IV vs. I: OR = 0.012, 95% confidence interval [CI] = 1.31–7.58, p = 0.012), T classification (T2 vs. T1: OR = 1.88, 95%CI = 1.28–2.79, p = 0.001), and cancer status (OR = 1.73, 95%CI = 1.12–2.71, p = 0.014)." (PMID 33411689, 2020). "Elevated RRM2 expression is a feature of many cancers, and a series of RNR inhibitors with different mechanisms can serve as effective drugs for cancer treatment." (PMID 40510157, 2025). "The prevalence of RRM2's high expression across various cancers further solidifies its role as a facilitator of tumorigenesis and a strategic point of intervention for cancer treatment." (PMID 39248068, 2025). "The RRM2 immunohistochemical score (H-SCORE) was significantly higher in PTC tissues than in paired paracancerous tissues (P<0.01), and the percentage of cancer tissues with higher RRM2 H-SCORE than paracancerous tissues was 81.8% (36/44)." (PMID 41333212, 2025). "RRM2 plays an important role in the development of various cancers, but its effect on the biological behavior of THCA is still unclear and needs to be further explored." (PMID 41333212, 2025). "TMZ‐resistant cells have higher iron levels and enhanced RRM2, making them vulnerable to iron chelation and offers a potential approach in cancer therapy." (PMID 40285641, 2025). "The RRM2 gene encodes the regulatory subunit M2 of ribonucleotide reductase (RNR), an enzyme of paramount importance in cancer treatment." (PMID 41357570, 2025). "Recent studies have highlighted the critical role of the ribonucleotide reductase subunit M2 (RRM2) gene in the occurrence and progression of various human cancers, including LUAD." (PMID 41357570, 2025). "This overexpression is also prevalent in various cancers that exhibit chemotherapy resistance, where RRM2's upregulation activates complex signaling pathways that regulate survival, growth, apoptosis, and chemoresistance in cancer cells." (PMID 39248068, 2025). "RRM2 is a member of the ribonucleoside diphosphate reductase small chain family, which plays important roles in cancer proliferation." (PMID 40303288, 2025). "The prediction and analytical exploration of upstream miRNAs targeting RRM2 has shedlight on potential regulatory mechanisms involving ncRNAs, which are recognized for their role in modulating gene expression in cancer." (PMID 41357570, 2025). "Ribonucleotide reductase M2 subunit (RRM2) is overexpressed through unclear mechanisms in many types of human cancer significantly affects sensitivity to various chemotherapy treatments." (PMID 41455715, 2025). "One recent pan-cancer analysis has identified a novel lncRNA ribonucleotide reductase small subunit M2 (RRM2) that was overexpressed in thirty types of human cancers." (PMID 39119602, 2024). "To explore the oncogenic role of human RRM2, we analyzed the expression pattern of RRM2 in different cancer types using the Oncomine database." (PMID 38635758, 2024).
cancer (continued). "We performed a gene set enrichment analysis (GSEA) to explore the pathways regulated by RRM2 in pan-cancer cells." (PMID 38635758, 2024). "The overexpression of RRM2 augments tumor angiogenesis and contributes to the metastatic and invasive potential of human cancer cells." (PMID 39482766, 2024). "RRM2 was highly expressed in most cancers, and there was an obvious correlation between RRM2 expression and patient prognosis." (PMID 38635758, 2024). "The membrane RRM2-positive iCCA cells represented a malignant subpopulation with cancer stem cell features." (PMID 39243109, 2024). "This study aimed to explore the potential carcinogenesis of RRM2 in pan-cancer using datasets from The Cancer Genome Atlas (TCGA)." (PMID 38635758, 2024). "In summary, these findings provide strong evidence that RRM2 is involved in the progression of cancer." (PMID 39766842, 2024). "Given their role in DNA synthesis and repair, RRM1 and RRM2 are attractive targets for novel cancer therapies." (PMID 39682247, 2024). "The phenomenon of increased expression of Ribonucleotide-diphosphate reductase M2 subunit (RRM2), a critical protein involved in the processes of DNA replication and repair, has been documented in various types of cancerous tumors." (PMID 39256879, 2024). "In a recent study conducted in our laboratory, a thorough examination was undertaken to assess the carcinogenic properties of RRM2 across various types of cancer." (PMID 39256879, 2024). "The results revealed that the cell cycle pathway was the most significantly affected by RRM2 expression in pan-cancer, and this was consistent with the KEGG enrichment analyses." (PMID 38635758, 2024). "Previous reports indicated that the antisense molecules to RRM2 effectively decreases RRM2 expression, inhibits enzyme activity and reduces growth of cancer cells in vitro and in vivo." (PMID 38992695, 2024). "Despite the involvement of RRM2 in multiple cancer types, our current understanding of its expression profiling, mechanisms, and role in MB remains limited." (PMID 40625451, 2024). "Various studies have shown that targeting RRM2 prompts cell senescence, cell arrest, or cell death in a variety of cancers." (PMID 39437704, 2024). "Data from the UCSC Xena database were analyzed to investigate the differential expression of RRM2 across multiple cancer types." (PMID 38635758, 2024). "The dysregulation of RRM2 has been found to be correlated with elevated mortality rates in numerous cancer patients." (PMID 39256879, 2024). "Our pan-cancer study provides a comprehensive understanding of the carcinogenesis of RRM2 in various tumors." (PMID 38635758, 2024). "In our previous investigation, it was postulated that the gene RRM2 exhibits elevated expression levels in several categories of malignant tumors, particularly in HBV-related HCC." (PMID 39256879, 2024). "Once entry into the cancer cells was achieved, siRNA silenced the anti-apoptotic factor M2 subunit of ribonucleotide reductase (RRM2)." (PMID 38992695, 2024). "The ribonucleotide reductase subunit M2 (RRM2) has the potential to be a useful prognostic biomarker in various types of cancer." (PMID 38699434, 2024). "The sorted membrane RRM2+ cells exhibited phenotypic features and molecular features of cancer malignancy and stemness." (PMID 39243109, 2024). "Overexpression of RRM2 enhances the metastatic and invasive capacity of human cancer cells and leads to poor prognosis in patients." (PMID 38992695, 2024). "Nevertheless, the specific immunotherapeutic role of RRM2 in immune checkpoint blockade requires further pan-cancer studies." (PMID 38635758, 2024). "Overall, these results indicated that RRM2 is highly expressed in most cancers and plays a potential oncogenic role." (PMID 38635758, 2024). "Here, we demonstrate that RRM2 expression is closely related to immune checkpoint genes in various cancers." (PMID 38635758, 2024).